CARMIL2 (capping protein regulator and myosin 1 linker 2)
Diseases named in the same sentence as CARMIL2 in open-access papers (continued):
Sharing a sentence is not in itself a finding about the gene and the disease.
diphtheria (1 paper, 2023). A Gram-positive bacterial infection caused by Corynebacterium diphtheriae. "Despite generally normal Ig concentrations, CARMIL2-deficient individuals displayed abnormally weak-specific Ab responses to protein-based booster vaccines, as 23/32 (72%) and 15/15 (100%) of the patients had low titers or no Abs against tetanus and diphtheria toxoid, respectively." (PMID 36515678, 2023).
leiomyomatosis (1 paper, 2017). A condition characterized by the presence of numerous small benign smooth muscle neoplasms located throughout the body. "Further studies may unravel why EBV causes leiomyomatosis rather than B-cell proliferation in CARMIL2-deficient patients." (PMID 28112205, 2017).
lower respiratory tract infections (1 paper, 2023). "Recurrent upper and lower respiratory tract infections were noted in 53/87 (61%) and 53/87 (61%) CARMIL2-deficient individuals, respectively." (PMID 36515678, 2023).
lymphoproliferative disorder (1 paper, 2017). "On the other side, even in the absence of EBV+ lymphoproliferative disorder, we found that CARMIL2-deficient T cells also had decreased capacity to recognize EBV+ autologous LCL." (PMID 28112205, 2017).
Pneumocystis infections (1 paper, 2024). "As dogs are affected by both the CARMIL2 variant and Pneumocystis infections, they represent a valuable natural model for studying the impact of this PI and host immune responses to Pneumocystis." (PMID 38535207, 2024).
pneumonia (1 paper, 2024). An acute, acute and chronic, or chronic inflammation focally or diffusely affecting the lung parenchyma, caused by an infection in one or both of the lungs (by bacteria, viruses, fungi, or mycoplasma.). "Deleterious CARMIL2 variants have recently been reported in human patients with PCP and other recurrent pneumonias." (PMID 38535207, 2024). "CARMIL2 deficiencies are also a potential underlying risk factor for PCP and other recurrent pneumonia in humans." (PMID 38535207, 2024). "The purpose of this study was to describe the discovery and clinical presentation of a PI attributed to a CARMIL2 nonsense variant in two CKCSs affected by Pneumocystis canis pneumonia and one CKCS with refractory pneumonia caused by the respiratory pathogen Bordetella bronchiseptica." (PMID 38535207, 2024).
Respiratory tract infection (1 paper, 2024). An infection of the upper or lower respiratory tract. "However, recurrent respiratory tract infection has also been reported as one of the most common infectious manifestations of CARMIL2 deficiencies." (PMID 38535207, 2024).
visceral leishmaniasis (1 paper, 2025). A severe form of leishmaniasis characterized by irregular bouts of fever, substantial weight loss, swelling of the spleen and liver, and anemia (which may be serious). "Uniquely, our study sheds light on the first documented case of frequent relapsing visceral leishmaniasis attributed to a CARMIL2 mutation." (PMID 41207919, 2025). "We describe the clinical and genetic features of five patients from Palestine with homozygous CARMIL2 mutations, including the first documented case of recurrent visceral leishmaniasis associated with this gene defect." (PMID 41207919, 2025). "The uniqueness of the study lies in its documentation of the first reported case of recurrent visceral leishmaniasis attributed to a CARMIL2 mutation, emphasizing the importance of genetic investigations in understanding complex immunodeficiency disorders." (PMID 41207919, 2025). "By reporting the first documented case of recurrent visceral leishmaniasis linked to CARMIL2 mutation, the research expands the global knowledge base of this rare disorder and its variable clinical presentations." (PMID 41207919, 2025). "It is crucial to consider CARMIL2 as part of the diagnostic evaluation for individuals suspected of having recurrent respiratory, mucocutaneous, and atypical infections such as recurrent visceral leishmaniasis." (PMID 41207919, 2025). "Notably, one adult male developed recurrent visceral leishmaniasis, an unusual presentation not previously reported in the context of CARMIL2 deficiency." (PMID 41207919, 2025).
tumor (4 papers, 2017 to 2025). "Since CD28 co-signalling is essential to activate naive T cells and to induce Teff responses, EBV+ SMT in the context of CARMIL2-deficiency might evade anti-tumour immunity and indicate a particular importance of CD28 co-signalling in controlling this tumour entity." (PMID 28112205, 2017). "Analysis of Cd28−/− and Carmil2−/− mouse cohorts showed that both CD28 and CARMIL2 molecules were essential for antitumor rejection since their absence permitted BRAFV600EPtgs−/− tumor growth, whereas Carmil2QE mice rejected the BRAFV600EPtgs−/− tumor as efficiently as WT mice." (PMID 40402149, 2025).
cancer (1 paper, 2025). A tumor composed of atypical neoplastic, often pleomorphic cells that invade other tissues. "On the other hand, the increased candidates included proteins involved in the blockade of cancer cell migration and invasion (SCAI, CARMIL2), autophagy activation (HSBP1, RILP) as well as proteins that can be considered as anti-tumorigenic (SCG2, DIP2A, HSBP1)." (PMID 39833546, 2025).
genetic disorder (1 paper, 2025). "The presented case series provides a comprehensive overview of five individuals diagnosed with CARMIL2 mutations, explaining the diverse clinical manifestations associated with this rare genetic disorder." (PMID 41207919, 2025).
infectious disease (1 paper, 2023). A disorder directly resulting from the presence and activity of a microbial, viral, or parasitic agent in humans. "CARMIL2-deficient individuals therefore suffered from a plethora of infectious diseases." (PMID 36515678, 2023).
CARMIL2 also shares sentences with these, for which no sentence is quoted: infection (2 papers); skin abscesses (2); viral infection (2); abscess (1); acute T cell leukemia (1); asthma (1); ataxia telangiectasia (1); Candida infection (1); chronic mucocutaneous candidiasis (1); Clouston syndrome (1); eosinophilic gastrointestinal disease (1); Food allergies (1); fungal infectious disease (1); gastrointestinal disease (1); Herpesviridae infections (1); hypogammaglobulinemia (1); inflammation (1); inflammatory myopathy (1); leiomyoma (1); lymphoma (1); Netherton syndrome (1); Obesity (1); onychomycosis (1); otitis media (1); respiratory allergies (1); respiratory infection (1); retinitis (1); ulcer (1); vaginitis (1); varicella zoster virus infections (1).
A further 1 disease shares a sentence with CARMIL2 in 1 paper.